BIRC5 (baculoviral IAP repeat containing 5)
Diseases named in the same sentence as BIRC5 in open-access papers (continued):
Sharing a sentence is not in itself a finding about the gene and the disease.
non-small cell lung carcinoma (10 papers, 2018 to 2025). A group of at least three distinct histological types of lung cancer, including non-small cell squamous cell carcinoma, adenocarcinoma, and large cell carcinoma. "In patients with non-small cell lung cancer with COVID-19, BIRC5, a member of the inhibitor of apoptosis (IAP) gene family, may be a target gene with important predictive significance." (PMID 37426635, 2023). "Some other genes, such as BIRC5, BLM, and CCNB2, are also differentially expressed in non-small-cell lung cancer." (PMID 33346087, 2020).
breast tumor (9 papers, 2011 to 2024). "Over expression of BIRC5 gene has been reported to be correlated with loss of specific chromosomal regions in breast tumor cells." (PMID 27876019, 2016). "It is now possible to suggest that BIRC5 could serve as a potential target for the diagnostic and prognostic biomarker for the detection, diagnosis, or prognosis of breast tumor patients." (PMID 36358602, 2022). "The gene signature associated with high 14-3-3ζ levels in breast tumors encompassed many with functions in mitosis and cytokinesis, including aurora kinase-B, polo-like kinase-1, CDC25B, and BIRC5/survivin." (PMID 21707964, 2011). "Previous studies examined peripheral blood from BC patients to look for the presence of BIRC5 in circulating breast tumor cells and revealed that, out of 67 patients, 34 patients (50.7%) had breast tumor cells that expressed BIRC5 in their peripheral blood samples but not in healthy samples." (PMID 36358602, 2022). "High expression of BIRC5 may contribute to breast tumor proliferation by promoting genetic instability." (PMID 33431968, 2021). "Significantly increased mRNA levels were found in breast tumors compared to healthy controls for UBE2T, UBE2C, BIRC5, TCEB2." (PMID 33671201, 2021). "Five of these genes (NEK2, PLK, BIRC5, TPX2 and AURKA) displayed DNA amplification (or polysomy) in more than 30% of breast tumors." (PMID 21352579, 2011). "Univariate, continuous BIRC5 expression was higher in breast tumors from Black women relative to non-Black women in both estrogen receptor (ER)-positive and ER-negative tumors and in analyses stratified by stage (i.e., within Stage I, Stage II, and Stage III/IV tumors)." (PMID 38515208, 2024).
lung squamous cell carcinoma (9 papers, 2017 to 2023). "Interestingly, higher BIRC5 expression was associated with better OS in lung squamous cell carcinoma and ovarian serous cystadenocarcinoma." (PMID 35331169, 2022). "For instance, the miR-195 axis regulates lung squamous cell carcinoma (LUSC) progression through BIRC5." (PMID 31992202, 2020). "BIRC5 protein expression in tumor tissue versus normal tissue was 1.3 times more often elevated in the squamous cell lung cancer group." (PMID 29190974, 2017). "The mRNA expression of BIRC5, SHCBP1, CCNA2, SKA3, and GINS1 in LUAD and lung squamous cell carcinoma (LUSC) tissues were all significantly higher than that in normal tissues." (PMID 34806315, 2022). "Among patients with lung squamous cell carcinoma (LUSC), the expression level of BIRC1 was lower and that of BIRC5 was higher than those in normal tissues, and BIRC5 expression significantly varied in different stages." (PMID 34925455, 2021).
acute myeloid leukemia (8 papers, 2019 to 2026). Acute myeloid leukemia (AML) is a group of neoplasms arising from precursor cells committed to the myeloid cell-line differentiation. "In a cohort of individuals with acute myeloid leukemia, low BIRC5 expression was also associated with statistically significant longer overall survival." (PMID 36358602, 2022). "Another neoplasm in which STAT3 has been linked to Birc5 is acute myeloid leukemia (AML)." (PMID 33557010, 2021). "BIRC5 is a well-known biomarker for tumor progression as it promotes cell proliferation and overall rates of survival and is associated with poor clinical outcome in patients with acute myeloid leukemia (AML)." (PMID 34574442, 2021). "Taken together, silencing BIRC5 expression by CRISPR/Cas9n may hold clinical therapeutic promise to rescue acute myeloid leukemia by suppressing uncontrolled growth of these cells." (PMID 31104397, 2019). "In acute myelocytic leukemia (AML), knock-down of BIRC5 induces apoptosis and is therefore regarded as a potential therapeutic target for AML patients." (PMID 31626592, 2019). "Furthermore, the disruption of BIRC5 by CRISPR inhibited the progression of other malignancies, such as Acute Myelocytic Leukemia." (PMID 33669949, 2021). "This study found that FGNs could treat acute myeloid leukemia subtype 2 (AML-M2) by silencing five essential oncogenes (BAG1, MDM2, Bcl-2, BIRC5, and XIAP) in AML-M2." (PMID 36612296, 2023).
myeloma (8 papers, 2014 to 2024). "Over-expression and knockdown studies in human myeloma cell lines have implicated BIRC5 in proliferation and protection of MM cells from apoptosis." (PMID 26445238, 2015). "In MM, BIRC5 expression, detectable in 43% of myeloma cell samples, is associated with proliferation, prognostically adverse chromosomal aberrations (del17p and gain of 1q21), and gene expression based high-risk scores." (PMID 25296978, 2014). "Except that, downregulating BIRC5 improved the efficiency of anti-myeloma drugs and triggered cell apoptosis, thereby developing the therapeutic benefit for multiple myeloma." (PMID 35461228, 2022). "MAGEA3 has previously been described to prevent apoptosis through the upregulation of BIRC5 (Survivin), a member of the inhibitor of apoptosis family, in multiple myeloma." (PMID 34166362, 2021). "High levels of Baculoviral inhibitor of apoptosis repeat-containing 5 (BIRC5/Survivin) expression in multiple myeloma cells correlates with reduced Bim transcription in response to IL-6 deprivation and shorter overall survival of patients." (PMID 26405162, 2015). "In turn, BIRC5 is expressed in all samples of proliferating normal or malignant plasma cells, i.e. polyclonal plasmablastic cells (PPC, non-malignant, n = 10), or human myeloma cell lines (n = 32)." (PMID 25296978, 2014).
osteosarcoma (8 papers, 2017 to 2025). A usually aggressive malignant bone-forming mesenchymal neoplasm, predominantly affecting adolescents and young adults. "Through screening, Mifepristone, which can act on BIRC5 and IL1β at the same time, has a very effective osteosarcoma treatment effect." (PMID 40616392, 2025). "The prominent anti-apoptotic molecule, i.e., survivin (BIRC5), was identified as a gene highly expressed in osteosarcoma tissues and involved in osteosarcoma development." (PMID 36139691, 2022). "It was also found that the survivin levels (BIRC-5) are lowered in osteosarcoma cells compared to the HeLa cell line." (PMID 36139691, 2022). "RNA-seq studies demonstrated that YAP as well as YAP-regulated genes, such as Cyr61, THBS1, PAI-1 and BIRC5, are significantly overexpressed in tissues derived from osteosarcoma patients as compared to normal bone tissues." (PMID 34440844, 2021). "Bioinformatics analysis identified six exosome‐associated osteosarcoma genes (WNT5A, GCA, ANXA6, BIRC5, IL1β, and ARPC3) that could serve as potential biomarkers." (PMID 40616392, 2025). "Gene coding of the survivin (BIRC5) is upregulated in various malignancies, including osteosarcoma." (PMID 36139691, 2022). "In osteosarcoma, NR2F1-AS1 accelerates proliferation and apoptosis resistance through both the miR-485-5p/miR-218-5p/BIRC5 and miR-483-3p/FOXA1 axes." (PMID 40828427, 2025). "In osteosarcoma, NR2F1-AS1 enhances cell motility through miR-483-3p/FOXA1 and miR-485-5p/miR-218-5p/BIRC5 pathways, contributing to ECM degradation and metastasis." (PMID 40828427, 2025). "The expression profiles of six core genes (WNT5A, GCA, ANXA6, BIRC5, IL1β, and ARPC3) were contrasted between the control and osteosarcoma groups." (PMID 40616392, 2025). "Another study showed that miR-485-5p can downregulate the expression of baculoviral IAP repeat containing 5 (BIRC5) and block the malignant phenotype of osteosarcoma." (PMID 35692754, 2022). "Furthermore, we were able to show that viscum, TT, and viscumTT led to downregulation of BIRC5 and XIAP in AML, Ewing-sarcoma, and osteosarcoma." (PMID 28791312, 2017).
esophageal cancer (7 papers, 2014 to 2022). A primary or metastatic malignant neoplasm involving the esophagus. "While rs17878467 increased BIRC5 promoter activity in HeLa cell lines, rs8073069 was associated with overexpression of survivin in the esophageal cancer." (PMID 31438837, 2019). "In our study, microarray data showed that three genes (FOS, JUN, BIRC5) associated with the anti-apoptotic response were elevated in the cisplatin-treated esophageal cancer cells." (PMID 24959694, 2014). "BIRC5 knockdown decreased cell proliferation and induced apoptosis in oesophageal cancer cells, whereas PRKCI silencing decreased proliferation, migration, invasion and growth of anchorage-independent colonies of oesophageal cancer cells and induced apoptosis." (PMID 32429269, 2020). "Our data also showed the up-regulation of proteins such as HSP70, BCL-2 and BIRC5 in the cisplatin-treated esophageal cancer cells, indicating an increase in the anti-apoptotic molecular pattern." (PMID 24959694, 2014). "Similarly, KLF4 decreased cell viability following ROS-induced DNA damage, increased anoikis and repressed pro-survival baculoviral IAP repeat-containing 5 (BIRC5) in esophageal cancer cells." (PMID 35406507, 2022). "We noted that compared to normal tissue, BIRC5, CENPF, STMN1, APOC2, and HNRPC were the five most significantly upregulated genes in esophageal cancer." (PMID 33828156, 2021). "The comparison between esophageal tumors and healthy tissue showed BIRC5 (p = 2.61E−08), APOC2 (p = 3.23E−08), CENPF (p = 4.38E−08), STMN1 (p = 5.74E−08), and HNRPC (p = 8.21E−08) to be five leading genes overexpressed in esophageal cancer." (PMID 33828156, 2021).
sarcoma (7 papers, 2018 to 2024). A usually aggressive malignant neoplasm of the soft tissue or bone. "Finally, a prognostic model for sarcoma patients was constructed using six hub genes: risk score = 0.05 × VEGFA + 0.25 × HMGB3 + 0.22 × FASN + 0.40 × RCC1 + 0.46 × NETO2-0.10 × BIRC5." (PMID 38240704, 2024). "Therefore, we speculated that BIRC5 may be a robust diagnostic and therapeutic biomarker for sarcoma." (PMID 33435917, 2021). "Except for prostate adenocarcinoma, sarcoma, cutaneous melanoma, thyroid carcinoma, and thymoma, BIRC5 was significantly elevated (p < 0.05) in all nineteen cancers based on the pan-cancer analysis results." (PMID 36358602, 2022). "We evaluated our mouse models of synovial sarcoma for Birc5 gene expression and found increased levels of transcript in the sarcoma tissue compared to normal skeletal muscle (p = 1.4 × 10−4)." (PMID 30909651, 2019). "BIRC5 accounted for 4.6% of amplification frequency of TCGA sarcoma." (PMID 29459674, 2018). "We also performed a t-test analysis for each BIRC5, ERBB2 and EZH2 in TCGA sarcoma, uterine corpus endometrial carcinoma and ovarian serous cystadenocarcinoma." (PMID 29459674, 2018). "Both BIRC5 and ERBB2 genes generated a significant result with P-value < 2.2e-16 in both TCGA sarcoma and uterine corpus endometrial carcinoma." (PMID 29459674, 2018).
Ewing sarcoma (6 papers, 2016 to 2025). A small round cell tumor that lacks morphologic, immunohistochemical, and electron microscopic evidence of neuroectodermal differentiation. "Since BIRC5 expression is associated with chemo- and radioresistance in Ewing sarcoma and poor patient prognosis, BIRC5 downregulation by Viscum album L. extracts makes it an interesting candidate for targeting Ewing sarcoma." (PMID 27589063, 2016). "The overexpression of BIRC5 in Ewing sarcoma was an independent adverse prognostic factor." (PMID 38240704, 2024). "Mistletoe extracts also reduced XIAP and BIRC5 expression in Ewing sarcoma cells." (PMID 27589063, 2016). "Here we demonstrate that reconstituting the aqueous and triterpene components from mistletoe in the viscumTT extract synergistically induces caspase-dependent apoptosis associated with CLSPN, MCL1, BIRC5 and XIAP downregulation in Ewing sarcoma cell lines in vitro and primary cells ex vivo." (PMID 27589063, 2016).
ovarian tumor (6 papers, 2017 to 2022). "Our data indicate that BIRC5 expression is potentially associated with ovarian tumor metastasis by promoting EMT." (PMID 29212257, 2017). "We demonstrated here that miR-203 expression inhibits ovarian tumor metastasis by suppressing EMT through targeting BIRC5, in addition through targeting Snai2." (PMID 30241553, 2018). "miR-203 inhibits ovarian tumor metastasis by targeting BIRC5/survivin and attenuating the TGFβ pathway." (PMID 30241553, 2018). "Histone modifications by acetylation with aberrant tubulin protein expression, reduction of PACE3 expression, silencing of survivin (BIRC5), upregulation of pRb tumor suppressor gene and CDKN1 (Cyclin-dependent Kinase) were reported in ovarian tumor formation." (PMID 36092905, 2022).
squamous cell carcinoma (6 papers, 2017 to 2025). A carcinoma arising from squamous epithelial cells. "BIRC5 was inversely associated with the characterization of antigen processing machinery and survival expression in tonsillar squamous cell carcinoma." (PMID 35860570, 2022). "The factors that independently increased the risk of OS shortening included diagnosis of squamous cell carcinoma (HR = 2.10, 95% CI: 1.04–4.28, p = 0.0406) and GG genotype of the BIRC5 gene (HR = 3.63, 95% CI: 2.05–6.43, p < 0.0001)." (PMID 35326407, 2022). "In contrast, higher risk of PFS shortening was independently associated with the histopathological diagnosis of squamous cell carcinoma (HR = 2.85, 95% CI: 1.24–6.54, p = 0.0138) and the GG genotype of the BIRC5 gene (HR = 1.92, 95% CI: 1.15–3.24, p = 0.0136)." (PMID 35326407, 2022). "Specifically, we found that BIRC5, which codes for survivin, is upregulated in both adenocarcinoma and squamous cell carcinoma tissues and that high expression of BIRC5 is associated with poor survival in adenocarcinoma, but not squamous cell carcinoma." (PMID 29416000, 2018). "Birc5, which is transcriptionally upregulated during squamous cell carcinomas, exerts its function by inhibiting caspase activation, thereby blocking apoptosis." (PMID 29109723, 2017). "In squamous cell carcinoma, miR-483-3p sensitized cells to apoptosis by targeting anti-apoptotic genes such as API5, BIRC5, and RAN." (PMID 40537919, 2025).
lymphoma (5 papers, 2008 to 2024). A malignant (clonal) proliferation of B- lymphocytes or T- lymphocytes which involves the lymph nodes, bone marrow and/or extranodal sites. "According to the dominant inheritance model, BIRC5-GC genotypes were associated with higher odds and an increased risk of developing lymphoma." (PMID 36831357, 2023). "The BIRC5-GC genotype was significantly associated with an increased risk of lymphoma in patients compared to controls." (PMID 36831357, 2023). "According to the study’s findings, the BIRC5-GC genotype is strongly linked to a patient’s vulnerability to developing lymphoma, and the BIRC5-AA genotype is also strongly linked to lymphoma susceptibility." (PMID 36831357, 2023). "In the codominant inheritance model, the BIRC5-GC genotype was significantly associated with an increased risk of lymphoma by 1.64-fold (95% CI: 1.26–2.14) and 2.98 times (95% CI: 1.68–5.28) in cases compared to controls." (PMID 36831357, 2023). "According to the dominant inheritance model, the BIRC5-GG and BIRC5 (GC + CC) genotypes were linked to higher odds and an increased risk of lymphoma in cases compared to controls of 3.09 (95% CI = 1.754–5.46) and 1.68 (95% CI = 1.29–2.19), respectively." (PMID 36831357, 2023). "BIRC5, which encodes survivin, is located on the 17q arm and is upregulated in resistant lymphoma cells and contributes to their proliferation." (PMID 35596920, 2022). "The survivin-GC and BIRC5-GG + CC genotypes were significantly related to lower odds of lymphoma risk in the dominant inheritance model (OR = 0.35, 95% CI = 0.20–0.61), and the chance was significantly lower in cases than in controls by 0.88 times (95% CI = 0.64–1.23)." (PMID 36831357, 2023). "The BIRC5-GC and BIRC5-GG + CC genotypes were significantly related to lower odds of lymphoma risk in the dominant inheritance model (OR = 0.37, 95% CI = 0.21–0.65), and the chance was significantly lower in cases compared to controls by 0.62 times (95% CI = 0.48–0.82)." (PMID 36831357, 2023). "Similarly, the BIRC5–AA genotype was strongly associated with lymphoma risk, with odds of 6.0-fold (95% CI = 1.10–32.9) and an increased risk of 2.47 times (95% CI = 0.76–8.03) in cases compared to controls." (PMID 36831357, 2023). "The frequency of the C allele was higher in healthy controls than in lymphoma patients, making the BIRC5-rs9904341 G > C gene variation between lymphoma patients and controls statistically significant." (PMID 36831357, 2023). "A higher risk of lymphoma, notable NHL, was shown to be related to variations in the antiapoptotic genes BCL2-938 C > A, MCL1-rs9803935 T > G, survivin-rs17882231 G > C, and BIRC5-rs9904341 G > C, particularly among men aged more than 45 years." (PMID 36831357, 2023). "According to the dominant inheritance model, there is a substantial correlation between the BIRC5-GG and BIRC5 (GC + CC) genotypes, which increases the vulnerability of lymphoma patients." (PMID 36831357, 2023). "The C allele in BIRC5, G allele in MCL1, and the G allele in BIRC5 were all substantially associated with an elevated risk of lymphoma, with the exception of the BCL-2-A allele." (PMID 36831357, 2023). "The G > C genotype of BIRC5-rs9904341 was most prevalent in lymphoma patients (66%), whereas the GG genotype was more prevalent in controls (57%)." (PMID 36831357, 2023). "(ii) BIRC5 (baculoviral IAP repeat-containing 5 gene), an inhibitor of apoptosis (IAP gene family) is expressed in most tumours and in lymphoma, participates in the spindle checkpoint and associates with AURKB." (PMID 18416826, 2008). "Median expression levels were invariably higher for AURKB, BCAT1, BIRC5, BUB1B, PBK and RACGAP1 and lower for FOSB, MAP3K1 and RIN3 by qPCR in lymphoma versus normal B cell samples in both species." (PMID 24130802, 2013).